CD4 (CD4 molecule)
Diseases named in the same sentence as CD4 in open-access papers (continued):
Sharing a sentence is not in itself a finding about the gene and the disease.
tumor (continued). "Immunohistochemical analysis revealed increased infiltration of CD4+ and CD8+ T-cells in the tumor microenvironment, leading to significant tumor size reduction." (PMID 40428099, 2025). "After radiotherapy, they found more ‘naive-like’ CD4+ T cells and newly activated CD8+ T cells coming into the tumor area, as well as the death of existing cytotoxic T cells and the arrival of myeloid cells." (PMID 41550427, 2025). "CD4+ T cells (helper T cells) regulate immune responses and activate other immune cells, while CD8+ T cells (cytotoxic T cells) directly kill tumor cells and are pivotal for antitumor immunity." (PMID 40657253, 2025). "In xenograft mouse models, KLK2 × CD3 and KLK2-targeted CAR T cells exhibited antitumor activity accompanied by CD4+ and CD8+ T-cell tumor infiltration." (PMID 40627156, 2025). "When targeting T cells, FACS analysis revealed that the surface expression of PD‐1 on CD4+ and CD8+ T cells within the tumor was upregulated at a heightened level after abdominal infection." (PMID 39835710, 2025). "In our analysis, we observed that one specific subset of T cells, CD4 Tregs, increased in abundance in HER2+ tumors relative to other tumor types, whereas one subset of macrophages, Mac Col., decreased in relative abundance." (PMID 40161579, 2025). "Hematoxylin and eosin (H&E) staining confirmed tumor formation and immediate adjacent tissue sections were stained for infiltrating T cells using anti-CD3, CD4, and CD8 antibodies." (PMID 40067762, 2025). "Because many neoantigens elicit de novo CD4+ and CD8+ responses, these vaccines can reshape anti-tumor immunity in cancer patients and are likely to complement existing immunotherapies." (PMID 41514653, 2025). "MHC class II expressed on tumor cells suppresses T-cell function through binding to LAG-3, while it also activates an antitumor immune response by presenting tumor antigens to CD4-positive T cells." (PMID 40801643, 2025). "EZH2 functions as an inhibitor of CD4+ and CD8+ effector T-cell recruitment into the tumor microenvironment in pcALCL, favoring immune evasion, tumor progression and antitumor immunity, making it an interesting pharmacological target." (PMID 40565334, 2025). "This, in turn, has been demonstrated to result in the up-regulation of PD-L1 expression, the reduction of CD4 and CD8 T-cell activation and tumor infiltration, and the promotion of the growth of pancreatic ductal adenocarcinoma (PDAC) cells." (PMID 40598593, 2025). "This expression is mainly detected in activated T-reg cells within the CD4+ TIL population and potential tumor-reactive CD103+ CD39+ TILs among the CD8+ TIL population." (PMID 40649207, 2025). "In MCC, TILs consist mainly of the CD4+, CD8+, and regulatory T-cell (Treg) subpopulations, with these cells sustaining the immune responses against a developing tumor." (PMID 40227764, 2025). "Enhances activation of CD3+/CD4+, CD3+/CD8+ T lymphocytes and DCs in tumor tissues and lymph glands." (PMID 41246345, 2025). "Cell types such as macrophages, CD4+ and CD8+ T cells, and dendritic cells are known to play crucial roles in anti-tumor immunity." (PMID 40027823, 2025). "Based on canonical marker genes, 11 cell types were annotated, including tumor cells, CD8+ T cells, CD4+ T cells, fibroblasts, macrophages, endothelial cells, epithelial cells, stromal cells, monocytes, vascular smooth muscle cells, and glial cells." (PMID 40859981, 2025). "After ACTL treatment, the patient’s immune status dramatically reversed: the IFN-γ level surged to 32.4 pg/ml, and the CD4+/CD8+ ratio rose to 6.2, accompanied by significant regression of tumor lesions and eventual achievement of cCR." (PMID 40959071, 2025). "In particular, CD4+ T cell subsets, such as Tregs and T helper 17 (TH17) cells, play distinct roles in shaping anti-tumor responses." (PMID 40658684, 2025).
tumor (continued). "Once infused into the patient, these activated DCs prime and activate CD4+ (helper) and/or CD8+ (cytotoxic) T cells, enabling them to target tumor cells possessing the same antigens." (PMID 40723238, 2025). "High GDF-15 expression in tumours significantly reduces CD8+ cytotoxic and CD4+ T cells within the TME." (PMID 41294666, 2025). "Both CD4+ T‐helper and CD8+ T‐cytotoxic cells from mice with large tumours expressed slightly elevated activation (CD69) and proliferative (IFN‐γ, Ki67) markers compared to mice with small tumours, indicating metabolic changes." (PMID 40112892, 2025). "Tumor tissue was immunohistochemically stained to identify CD8+ T cells, CD4+ T cells, CD161+ NK cells, F4/80+ macrophages and pan-Cadherin positive (PC+) tumor cells." (PMID 39789356, 2025). "It is there that cDC that have either migrated from the tumor lesion or that reside in the TDLN and that have taken up tumor antigens, will prime antigen‐specific CD4+ and CD8+ T cells." (PMID 39668411, 2025). "In one method, the idea of utilizing the CD8 co-receptor in TCR-Ts is combined with the immune roles of CD4 and CD8 T cells in a synergistic anti-tumor response." (PMID 39941782, 2025). "Evidence suggests that the number of tumor-infiltrating lymphocytes (TIL), particularly activated CD4 + and CD8 + effector T cells, improves the prognosis of ESCC patients." (PMID 40411616, 2025). "Consistent with this, the regressing tumor exhibited a reduction in cell staining for lymphocyte markers such as CD3, CD4, and CD8 as well as the monocyte/macrophage marker CD68." (PMID 40594889, 2025). "In vivo experiments show that PTSK@CRM possesses a favorable tumor-targeting ability to effectively suppress tumor growth and increase the infiltration of immune cells, including CD8+ T cells, CD4+ T cells, M1-like macrophages, and mature dendritic cells." (PMID 41432057, 2025). "In-vitro experiments validated the effects of TTFields on tumor cells for CD4+ T cell and CD8+ T cell infiltration, as well as the expression of tumor immunogenic death related genes and chemokines." (PMID 40098106, 2025). "In an in vivo breast cancer model, Tα‐1 in conjunction with Epirubicin treatment markedly slowed down the growth of the tumor by decreasing IL10 produced by macrophages and increasing the quantity and quality of CD4+ and CD8+ T cells that infiltrate the tumor." (PMID 39748782, 2025). "Activated CD4+ T cells promote the differentiation of TAA-specific cytotoxic CD8+ T cells, which subsequently migrate back to the tumor site to orchestrate the targeted killing of residual malignant cells." (PMID 41264121, 2025). "While MTD AT/DT (IV) did not significantly alter T cell populations, oral MCT AT/DT-NE#E—particularly in combination with anti-PD1—significantly increased tumor-infiltrating CD45+, CD4+, and CD8+ T cells, and T cell activation in TDLNs." (PMID 40733080, 2025). "Within the TME, eosinophils activated by TNF-α and IFN-γ release chemokines such as CXCL9 and CXCL10, promoting CD4+ and CD8+ T cell infiltration and enhancing anti-tumor immune responses." (PMID 41200171, 2025). "Overall, this confirms that ASEs detected in T cells from Es reflect the enrichment of CD8+ TEX- and CD4+ TH1/TFH cells, which are well established to be tumor-reactive during ICB response." (PMID 41273175, 2025). "Nanoparticles loaded with IL-2 enhance Th1-biased CD4+ responses, boosting IFN-γ and IL-2 secretion while improving cytotoxic activity against tumor cells." (PMID 40860882, 2025). "Intratumoral cDC1 delivery prior to milder chemotherapy demonstrated significant increases in T-cell infiltration in the tumor, specifically increased CD3+, CD4+, and CD8+ T-cells as well as B-cells, γδ T-cells, and NKT cells." (PMID 40333343, 2025). "CD4+ CXCL13+ Tfh cells and CD8+ CXCL13+ T cells predominantly expanded among ICB-Rs, which we termed IRATs as tumor-responsive T cells (TRTs)." (PMID 40054456, 2025).
tumor (continued). "The presence of CD69− T cells—particularly CD4+ and CD8+ subsets—within the TME, is potentially impacting an effective anti-tumor response that improves RFS." (PMID 40361474, 2025). "The responders showed an increased population of circulating CD4+ and CD8+ T cells, along with enhanced CD8+ T cell infiltration into tumor tissues." (PMID 41024300, 2025). "These macrophages can release immunosuppressive cytokines that inhibit the regulatory and cytotoxic functions of CD4+ and CD8+ T cells, thus facilitating tumor growth." (PMID 41488655, 2025). "Studies using mouse models indicate that eliminating γδT cells or inhibiting PDL1 enhances infiltration and effectiveness of CD4+ and CD8+ T cells, slowing tumor growth." (PMID 40289760, 2025). "While not reaching statistical significance, higher colocalization between CD4 + or CD8 + T cells and tumor cells showed trends toward improved RFS (p = 0.064 and p = 0.071, respectively)." (PMID 40859352, 2025). "Immunohistochemical staining of the second resection specimen showed that tumor cells were positive for CD68, CD163, CD4, INI-1 and ATRX, Scattered focal positivity for lysozyme, and some positive for S-100 and LCA." (PMID 40231251, 2025). "Through this axis, as signal senders CD4 and CD8 T cells exhibited notable interactions with B cells, macrophages, and monocytes, highlighting their central role in the tumor immune microenvironment." (PMID 40315269, 2025). "Immune phenotyping of lymphoid compartments revealed that bardoxolone methyl administration led to a relative depletion of CD4+ T cells in the spleen, accompanied by a marked enrichment of CD8+ T cells within both the spleen and tumor microenvironment." (PMID 40732256, 2025). "In the tumor microenvironment (TME), 5%–30% of CD4+Foxp3+ Treg cells have been observed to highly express granzyme B—a feature absent in Treg cells from some mouse models—suggesting that granzyme B production enables Tregs to kill NK cells and CD8+ T cells." (PMID 40297580, 2025). "In mouse models, the infiltration of both CD4+ and CD8+ T cells is seen mainly in normoxic zones of the tumour, while the hypoxic zones lack tumour-infiltrating T cells." (PMID 40647497, 2025). "While CD4+ CAR T cells produce more cytokines and exhibit robust proliferative capacity upon tumor encounter, CD8+ CAR T cells show increased lytic activity." (PMID 41346587, 2025). "All of these immunotherapies have achieved significant therapeutic results in animal models by activating CD4+, CD8+, and NK cells to suppress tumor progression." (PMID 40076679, 2025). "By contrast, mice treated with the C‐PC, and to a greater extent the C‐P, CDK4/6i priming regimens displayed higher CD4+ and CD8+ T cell abundance versus either monotherapy and other treatment groups in all three tumor models." (PMID 40936164, 2025). "Considering the percentages of the other activating receptors ICOS, OX40, and 4-1BB by CD4+ T cells and CD8+ T cells, highest proportions were found in tumor-infiltrated T cells." (PMID 41221283, 2025). "Our findings demonstrate that tumor metabolism, specifically bile acid metabolism and glycolysis, also shapes the ITH of CD8+ and CD4+ TILs, respectively." (PMID 40523956, 2025). "In order to evaluate the expression levels and topographic distribution profiles of CD4, CD8, Foxp3, CD68, CD163, and CD11c, tissue microarrays of the invasive front as well as the tumor core of BCC and cSCC samples were analyzed." (PMID 41068337, 2025). "In HPV+HNSCC, CD4+ Tfh cells can assist in efficiently activating TIL-B, thereby enhancing anti-tumor immunity." (PMID 40703522, 2025). "In terms of αβT lymphocyte abundance, proportions of tumor-infiltrated CD3+ and CD4+ T cells were significantly lower than in the two liquid compartments." (PMID 41221283, 2025).
tumor (continued). "While we observed differences in lymphocyte-derived cfDNA between tumor and healthy control samples, there remains a critical need to increase the resolution of immune cell subsets, such as CD8+ T cells, CD4+ T cells, and CD19+ B cells." (PMID 40468033, 2025). "Beyond angiogenesis suppression, HEBERSaVax treatment was associated with a significant increase in the infiltration of CD4+ and CD8+ T cells, a change consistent with immune-mediated tumor control." (PMID 41488668, 2025). "These EVs induce apoptosis in cytotoxic CD8+ T cells while protecting regulatory CD4+/CD25+ T cells, weakening the anti-tumor immune response and aiding tumor immune escape." (PMID 39949780, 2025). "Peripheral blood samples from tumor-bearing mice were stained with CD3, CD4, and VHH nanobody flow antibodies on D25." (PMID 39981247, 2025). "Analysis from the TIMER database unveiled that the expression of GINS1 in LIHC was correlated with several tumor-infiltrating immune cells including B cell, CD8+ T cell, CD4+ T cell, macrophage, neutrophil, and dendritic cell." (PMID 40123906, 2025). "In contrast, there was a decreased density of activated CD4 T cells (CD45RA+GITR+TOX-) and CD8 T cells (CD45RA+GzmB+TOX-) in proximity to tumor cells." (PMID 39803458, 2025). "Then using single-cell RNA sequencing within tumor tissues of HCC patients and mIHC, we found that the proportions of CD8+T cells and CD8+TRM cells generally increased while that of CD4+T cells significantly decreased following ICB treatment." (PMID 41438767, 2025). "cDC1s are the only APCs capable of transporting intact antigens to lymph nodes and initiating tumor-specific CD8+ T cell responses, and they can also present exogenous antigens to CD4+ T cells through MHC-II molecules." (PMID 41430039, 2025). "Future research aims to optimize therapeutic strategies by leveraging CD4+ T cell plasticity, functional specialization, and interactions within the TME to enhance anti-tumor immunity." (PMID 40660400, 2025). "For instance, the abundance of exhausted T-cyt cells (CD8 + CD39 + PD-1 +) in ccRCC was found to be positively correlated with the abundance of T-regs (CD4 + FOXP3 +) and PD-L1 + tumor cells." (PMID 39751643, 2025). "Given that cancer immunotherapy depends mainly on T-cell infiltration in the tumor immune microenvironment, we isolated CD3+ T cells, CD4+ T cells and CD8+ T cells from healthy human peripheral blood mononuclear cells (PBMCs) to performed a cytotoxicity assay." (PMID 41019041, 2025). "Concurrently, CD4+ T-helper (Th1) cells, activated by MHC class II-presented epitopes, secrete IFN-γ to enhance CTL activity and promote an inflammatory tumor microenvironment." (PMID 40514725, 2025). "This same pattern was evident for the low-tumor-burden (LTB) patients, those with <20% CD4+CD26− T cells as defined by Benoit." (PMID 40723261, 2025). "These inhibitors enhanced the tumor immune response by increasing the infiltration of CD8+ and CD4+ tumor-infiltrating lymphocytes (TILs)." (PMID 40343532, 2025). "PD-1 is an inhibitory co-receptor expressed on B-cells, NK, CD4+ and CD8+ T-cells, and tumor-infiltrating lymphocytes (TILs)." (PMID 40299416, 2025). "Consistent with this, within tumours we found FRC-like fibroblasts located with B-cells and (Tfh) CD4 + T-cells in TLS structures, correlating with several well-described TLS gene signatures." (PMID 39757146, 2025). "In LC immunotherapy, RNA‐LNPs promoted DCs maturation, which in turn activated tumor antigen‐specific CD8+ and CD4+ T cells." (PMID 41201063, 2025). "Following specific depletion using anti-CD4 and anti-CD8 antibodies, the anti-tumor effect of the combination therapy was assessed." (PMID 41229436, 2025). "On one hand, effector T lymphocytes, especially CD8+ cytotoxic T cells (CTLs), partake in direct killing of the tumor cells, while type 1 helper (TH1) CD4+ T cells assist in the recruitment and effectiveness of CTLs." (PMID 40820379, 2025).
tumor (continued). "Replaced suppressive CD163+ TAMs with immunostimulatory CD11chigh cells; increased CD4+/CD8+ T-cell infiltration and tumor regression." (PMID 40918451, 2025). "For all seven patients, CD3-positive, CD4-positive, and CD8-positive lymphocyte fractions were sorted from primary tumor, adjacent lung tissue samples and PBMCs." (PMID 40165973, 2025). "Functional scoring demonstrated marked impairment of cytotoxic potential in tumor-infiltrating lymphocytes, with significantly decreased “Cytotoxicity” scores in CD8 + T, CD4 + T, and NK cells compared to normal group." (PMID 41187171, 2025). "Spatial single-cell proteomic results showed that expanded CD4+ T cells and CD8+ T cells exhibited more pronounced co-localized in the tumor tissues of patients receiving combination therapy." (PMID 40385461, 2025). "Potential immunological correlations between key genes and tumor-infiltrating immune (including B cell, CD8+ T cell, CD4+ T cell, macrophage, neutrophil, and dendritic cell) were analyzed." (PMID 39928794, 2025). "For example, high-dose IL-2 binding to CD25 can enhance IL-2R signaling in CD4+and CD8+T cells in mice, improving the efficacy of vaccines against antigens and more effectively clearing tumor cells." (PMID 39958351, 2025). "This resulted in enhanced infiltration of CD4+ and CD8+ T-lymphocytes into the stroma, leading to subsequent tumor regression." (PMID 40918451, 2025). "We employed immunostaining for CD3, CD4, CD8, Granzyme B (GzmB), FOXP3, CD163, and CD68 markers to quantitively analyze the STR patient’s tumor immune landscape both at baseline and during STR 10–12." (PMID 40594889, 2025). "Altogether, the huCC49-IL-2 treatment resulted in the generation of a potent anti-tumor immune environment, as evidenced by the changes in IFNγ+CD8+ T to CD4+ T-reg ratios." (PMID 40361381, 2025). "This combination reduced Tregs and increased CD4+ and CD8+ T cells expressing IFN-γ, enhancing the anti-tumor immune response and inhibiting tumor growth in PDAC models." (PMID 40420798, 2025). "Tumor-infiltrating T cells are key immune components in the PDAC TME, comprising CD8+ effector T cells, CD4+ helper T cells, and regulatory T cells (Tregs)." (PMID 40420798, 2025). "Among these, CD4+/CD8+ TRM cells display heightened activation of TFs, underscoring their ‘effector memory’ characteristics and their potential for rapid tumor antigen response due to long-term residence in the BM microenvironment." (PMID 41155287, 2025). "Radiation has been shown to enhance the presentation of TAA by DCs to CD4+ and CD8+ T cells, thereby strengthening the immune system’s ability to recognize and target tumor cells." (PMID 39941769, 2025). "A recent study demonstrated the formation of CD4+ and CD8+ T cell interactions with the same cDC in tumours, forming a T cell‐cDC triad." (PMID 40878038, 2025). "To identify the anti-tumor immune cellular mechanism of NPRL2, we evaluated the antitumor effect of NPRL2 on LLC2 syngeneic tumors after depleting cytotoxic CD8+ T, CD4+ T, NK, and antigen-presenting macrophages and dendritic cells in mice." (PMID 39932765, 2025). "The results showed the strong association of target gene expression with the significant infiltration of tumor-targeting immune cells such as macrophages, CD8+ T cells, CD4+ T cells, and myeloid dendritic cells." (PMID 40647469, 2025). "We then applied three separate gene signatures to predict tumor reactivity: Lowery (CD4 and CD8 T cell prediction), Meng (CD8 T cell prediction), and Zheng (CD4 T cell prediction)." (PMID 40848148, 2025). "One of the most significant findings of our study is the enhanced infiltration of CD4+ and CD8+ T cells in tumor tissues following HO-1 inhibition." (PMID 40037158, 2025). "This interaction between CD4+ and CD8+ T cells is crucial for an effective anti-tumor immune response." (PMID 41007114, 2025).